ETV3 (ETS variant transcription factor 3)
Description:
Transcriptional repressor that contribute to growth arrest during terminal macrophage differentiation by repressing target genes involved in Ras-dependent proliferation. Represses MMP1 promoter activity.
Synonyms: PE-1; METS; PE1
Tractability: PROTAC: UniProt records ubiquitination sites on it; ubiquitination databases record sites on it.
Gene: Protein-coding gene on chromosome 1 (157,121,191 to 157,138,474, reverse strand). Ensembl gene ENSG00000117036.
Subcellular location: Nucleus
Subcellular location (Human Protein Atlas): Nucleoplasm; Cytosol; Nucleoli; Vesicles
Gene Ontology:
Molecular function: sequence-specific double-stranded DNA binding; DNA-binding transcription factor activity, RNA polymerase II-specific; DEAD/H-box RNA helicase binding; DNA-binding transcription factor activity; DNA-binding transcription repressor activity, RNA polymerase II-specific; RNA polymerase II transcription regulatory region sequence-specific DNA binding; sequence-specific DNA binding
Biological process: cell differentiation; regulation of transcription by RNA polymerase II; cellular response to granulocyte macrophage colony-stimulating factor stimulus; negative regulation of cell population proliferation; negative regulation of transcription by RNA polymerase II; regulation of DNA-templated transcription
Cellular component: chromatin; nucleus; RNA polymerase II transcription repressor complex; transcription repressor complex
Genetic constraint (gnomAD): Loss-of-function variants: 11 observed, 40.69 expected, observed/expected ratio (o/e) 0.27, 90% interval 0.17 to 0.45. The upper end of that interval is the gene's LOEUF score, 0.45, which puts it in group 1 of 6, group 1 being the genes least tolerant of losing a copy. Missense variants: 473 observed, 677.22 expected, observed/expected ratio (o/e) 0.7, 90% interval 0.65 to 0.75. Synonymous variants: 222 observed, 249.32 expected, observed/expected ratio (o/e) 0.89, 90% interval 0.8 to 1.
Homologues: Orthologues: chimpanzee ETV3 (99% identical), macaque ETV3 (98% identical), pig ETV3 (93% identical), guinea pig ETV3 (90% identical), dog ETV3 (89% identical), rat Etv3 (87% identical), mouse Etv3 (86% identical), tropical clawed frog etv3 (64% identical). Paralogues in human: ERF (45% identical), ETV3L (32% identical), ERFL (25% identical), ELK4 (17% identical), ELK1 (17% identical), ELK3 (16% identical), ERG (15% identical), FLI1 (15% identical), ELF1 (15% identical), ELF4 (14% identical), ELF2 (14% identical), ETS1 (13% identical), and 16 more.
Diseases named in the same sentence as ETV3 in open-access papers:
ETV3 is named in the same sentence as 27 diseases in open-access papers, as found by Europe PMC text mining. Sharing a sentence is not in itself a finding about the gene and the disease. The quoted sentences say what the papers report.
breast carcinoma (3 papers, 2023 to 2024). "Recently, amplification of ETV3 has been reported in breast cancer, supporting copy number gain as potent activating mechanism of this oncogene." (PMID 37428779, 2023). "It is possible that downregulation of FASN by 1E5 may similarly increase ETV3/PEA3 in HER2-positive breast cancer cells." (PMID 38730603, 2024).
anaplastic large cell lymphoma (1 paper, 2023). Anaplastic large cell lymphoma (ALCL) is a rare and aggressive peripheral T-cell non-Hodgkin lymphoma, belonging to the group of CD30-positive lymphoproliferative disorders, which affects lymph nodes and extranodal sites. "The LL-100 RNA-seq dataset showed elevated ETV3 expression in 4/6 HL cell lines and additionally in 4/4 cell lines derived from anaplastic large cell lymphoma (ALCL)." (PMID 37428779, 2023).
craniosynostosis (1 paper, 2018). Craniosynostosis is defined as the premature fusion of one or more cranial sutures leading to secondary distortion of skull shape resulting in skull deformities with a variable presentation. "Out of seven genes with a high (< 10%) or moderate (< 25%) HI score (NES, CCT3, MEF2D, LAMTOR2, ETV3, SSR2, NTRK1), none of them have been linked to craniosynostosis." (PMID 29845577, 2018).
dendritic cell tumor (1 paper, 2021). A dendritic cell tumor develops from the cells of the immune system. "Other genes to which DVRs were annotated were also related to the lymphatic or hematopoietic systems such as the gene ETV3, associated to dendritic cell tumor, which develops from cells of the immune system, typically beginning in the lymph system." (PMID 33632303, 2021).
gastric cancer (1 paper, 2025). A primary or metastatic malignant neoplasm involving the stomach. "ETS family members with the highest protein level of expression in many gastric cancer samples include ETV5, ETV4 and ETV3, while ELF2 and ELF3 had moderate to high levels of expression in all samples tested in the Human Protein Atlas but only in one of the two antibodies checked for each protein." (PMID 41425714, 2025).
lung adenocarcinoma (1 paper, 2025). A carcinoma that arises from the lung and is characterized by the presence of malignant glandular epithelial cells. "ETV3 (ETS Variant Transcription Factor 3), a member of the ETS transcription factor family, has been associated with tumor suppression in lung adenocarcinoma." (PMID 40559081, 2025).
lung carcinoma (1 paper, 2025). "In lung cancer, gene fusions involving ETV3 have been observed and may contribute to oncogenic transcriptional reprogramming." (PMID 40559081, 2025).
non-Hodgkin lymphoma (1 paper, 2010). Distinct from Hodgkin lymphoma both morphologically and biologically, non-Hodgkin lymphoma (NHL) is characterized by the absence of Reed-Sternberg cells, can occur at any age, and usually presents as a localized or generalized lymphadenopathy associated with fever and weight loss. "Additionally, the use of this method to analyse SNP microarray data from 3 common forms of non-Hodgkin's lymphoma yielded interesting tumor suppressor gene candidates, including the ETV3 gene that was highlighted in both B-CLL and FL." (PMID 20462409, 2010).
psoriasis (1 paper, 2016). An autoimmune condition characterized by red, well-delineated plaques with silvery scales that are usually on the extensor surfaces and scalp. "Therefore, ETV3 seems to be a good candidate for regulating psoriasis inflammation." (PMID 27774448, 2016). "Downregulation of ETV3 in psoriatic skin (lesional and non-lesional) indicates a suppression of anti-inflammatory signals for psoriasis." (PMID 27774448, 2016).
type 2 diabetes (1 paper, 2025). "In adipocyte 2, transcription factors associated with neurodegenerative diseases, type 2 diabetes, and cancer (Ctcfl, Etv3, Atf4, Zmiz1, Sp3) showed reduced activity in the old group." (PMID 40631796, 2025).
cancer (5 papers, 2019 to 2025). A tumor composed of atypical neoplastic, often pleomorphic cells that invade other tissues. "Interestingly, the two most strongly correlated genes, Etv3 and Zfp217, are transcription regulators shown by others to be associated with breast cancers, further suggesting that widespread transcriptional dysregulation promotes diversity in cancer phenotypes." (PMID 31240244, 2019). "EGR2 induces apoptosis in several cancer cell lines, ETV3 contributes to growth arrest, HES1 is involved in DNA interstrand crosslink damage repair and could participate in response to DNA adducts induced by DEN." (PMID 34383828, 2021).
tumor (4 papers, 2010 to 2025). "Dysregulation of ETV3 has been linked to tumor immune evasion, potentially influencing how tumor cells respond to systemic therapies." (PMID 40559081, 2025).
ETV3 also shares sentences with these, for which no sentence is quoted: acute lymphoblastic leukemia (1 paper); acute myeloid leukemia (1); autoimmune disease (1); chronic hepatitis B (1); Cirrhosis (1); colon cancer (1); hepatocellular carcinoma (1); Insulin resistance (1); lupus (1); mesenchymal chondrosarcoma (1); metabolic syndrome (1); multiple sclerosis (1); neurodegenerative disease (1); oral cancer (1); sarcopenia (1).